CDC42EP5 (CDC42 effector protein 5)
Description:
Probably involved in the organization of the actin cytoskeleton. May act downstream of CDC42 to induce actin filament assembly leading to cell shape changes. Induces pseudopodia formation in fibroblasts. Inhibits MAPK8 independently of CDC42 binding. Controls septin organization and this effect is negatively regulated by CDC42 (By similarity).
Synonyms: BORG3; CEP5
Tractability: Antibody: UniProt places it where antibodies can reach, with medium confidence; its Gene Ontology location is reachable by antibodies, with medium confidence.
Gene: Protein-coding gene on chromosome 19 (54,465,026 to 54,473,296, reverse strand). Ensembl gene ENSG00000167617.
Subcellular location: Endomembrane system; Cytoplasm, cytoskeleton
Subcellular location (Human Protein Atlas): Primary cilium; Cytosol; Nucleoplasm
Pathways (Reactome):
Signal Transduction: CDC42 GTPase cycle; MAPK6/MAPK4 signaling
Gene Ontology:
Molecular function: small GTPase binding
Biological process: positive regulation of actin filament polymerization; positive regulation of pseudopodium assembly; regulation of cell shape; Rho protein signal transduction
Cellular component: cytoplasm; membrane; cytoskeleton; cytosol; plasma membrane; endomembrane system
Genetic constraint (gnomAD): Loss-of-function variants: 3 observed, 0.92 expected, observed/expected ratio (o/e) 3.25. That is too few expected variants to judge how well the gene tolerates losing a copy. Missense variants: 242 observed, 118.01 expected, observed/expected ratio (o/e) 2.05. Synonymous variants: 108 observed, 58.6 expected, observed/expected ratio (o/e) 1.84, 90% interval 1.56 to 1.98.
Homologues: Orthologues: chimpanzee CDC42EP5 (100% identical), pig CDC42EP5 (89% identical), dog CDC42EP5 (86% identical), mouse Cdc42ep5 (80% identical), tropical clawed frog XB5748694 (45% identical), zebrafish cdc42ep5 (39% identical). Paralogues in human: CDC42EP4 (45% identical), CDC42EP1 (39% identical), CDC42EP2 (33% identical), CDC42EP3 (31% identical), C15orf62 (16% identical).
Diseases named in the same sentence as CDC42EP5 in open-access papers:
CDC42EP5 is named in the same sentence as 6 diseases in open-access papers, as found by Europe PMC text mining. Sharing a sentence is not in itself a finding about the gene and the disease. The quoted sentences say what the papers report.
melanoma (4 papers, 2020 to 2025). A malignant, usually aggressive tumor composed of atypical, neoplastic melanocytes. "The association between cell rounding and CDC42EP5 expression was consistent in other melanoma cell lines." (PMID 32798219, 2020). "Notably, Cdc42EP5 (also known as BORG3) has a similar role in melanoma metastasis as does Cdc42EP3 in promoting cancer-associated fibroblast activation." (PMID 39971161, 2025). "Importantly, CDC42EP5-associated phenotypes were extensible to other cell types, as similar results were obtained after depletion of CDC42EP5 in human melanoma cells (WM266.4) and in murine embryonic fibroblasts." (PMID 32798219, 2020). "To assess whether CDC42EP5 was functioning via septins to regulate actomyosin function and invasion in melanoma, we first analyzed whether there was any particular septin associated with melanoma aggressiveness." (PMID 32798219, 2020). "While the synergy or redundancy of Cdc42EP3 and SEPT9 remains to be determined, Cdc42EP5 has similar roles as SEPT9 in melanoma cells, where both Cdc42EP5 and SEPT9 are required for actomyosin-driven cell migration." (PMID 39971161, 2025). "Intriguingly, CDC42EP5 regulates melanoma cell motility, invasion and metastasis by virtue of its association with the actin cytoskeleton." (PMID 39138582, 2024). "In 3D collagen, Cdc42EP5 predominately localizes with active contractile actomyosin at the cell cortex in melanoma cells." (PMID 36438570, 2022). "Together, these data indicated that in 2D melanoma cells CDC42EP5 forms filamentous structures that overlap actin filaments and promotes the formation of perinuclear actomyosin fibers, leading to the maturation of FAs and increased cell motility." (PMID 32798219, 2020). "Together, these results indicate that CDC42EP5 is consistently required for melanoma migration and invasion in vitro and for local invasion and metastatic dissemination in vivo." (PMID 32798219, 2020). "Overall, these results confirm that Cdc42ep5 requires Sept9 interactions to promote actomyosin-dependent proinvasive behaviors in melanoma." (PMID 32798219, 2020). "Overall these results illustrate a unique role for Sept9 in controlling actomyosin structure and function in melanoma and place it as the key effector of CDC42EP5 functions in regulating migration, invasion, and metastasis." (PMID 32798219, 2020). "Here, we show that the septin regulator Cdc42EP5 is consistently required for amoeboid melanoma cells to invade and migrate into collagen-rich matrices and locally invade and disseminate in vivo." (PMID 32798219, 2020). "Together, these data indicated that CDC42EP5 promotes the generation of an actomyosin cortex, which impacts actomyosin activity and cell morphology, and induces invasive phenotypes in melanoma cells in 3D settings." (PMID 32798219, 2020). "Thus, silencing of Cdc42ep5 in melanoma cells seeded in 2D leads to the disassembly of higher-order Sept9 filaments, whereas in 3D results in reduced cortical Sept9." (PMID 32798219, 2020). "Having established a specific role for SEPT9 in regulating actomyosin contractility and invasion in melanoma, we next sought to investigate whether CDC42EP5 was modulating SEPT9 function in these processes." (PMID 32798219, 2020). "Here, we identify CDC42EP5 as a new regulator of melanoma invasion and metastasis." (PMID 32798219, 2020). "Our previous observations suggested that CDC42EP5 may be part of the actomyosin machinery that drives the maturation of focal complexes to FAs in melanoma." (PMID 32798219, 2020). "To further confirm that SEPT9 was a crucial effector of CDC42EP5 function in melanoma, we next investigated whether elevating Sept9 activity was sufficient to rescue the functional defects associated with loss of Cdc42ep5." (PMID 32798219, 2020). "Thus, we show a specific up-regulation of CDC42EP5 in rounded-amoeboid melanoma cells and describe a concomitant function of CDC42EP5 in modulating actomyosin activity in melanoma." (PMID 32798219, 2020).
melanoma (continued). "Still in 3D collagen, Cdc42EP5 interaction with SEPT9 increases NMII activity and is required for actomyosin-dependent melanoma invasion." (PMID 36438570, 2022). "We demonstrate that actomyosin function in melanoma is also dependent on the additional support provided by SEPT9 in those structures, which is modulated by the septin regulator CDC42EP5." (PMID 32798219, 2020). "This study provides evidence that Cdc42EP5 is a regulator of cancer cell motility that coordinates actin and septin networks and describes a unique role for SEPT9 in melanoma invasion and metastasis." (PMID 32798219, 2020). "No changes in melanoma proliferation or tumor growth were observed after modulating Cdc42ep5 expression." (PMID 32798219, 2020).
breast carcinoma (2 papers, 2020 to 2023). "In breast cancer cells, Cdc42ep3 or Cdc42ep5 have also been implicated in promoting the septin-actin association." (PMID 36923257, 2023). "We also describe that CDC42EP5 is required for migration and invasion in a mesenchymal model of breast cancer such as MDA-MB-231-LM2." (PMID 32798219, 2020).
cervical cancer (1 paper, 2025). A primary or metastatic malignant neoplasm involving the cervix. "To investigate CDC42EP5’s role in cervical cancer, we conducted in vitro experiments on Ca Ski and MS751 cells." (PMID 40777026, 2025).
prostate carcinoma (1 paper, 2025). A carcinoma that arises from epithelial cells of the prostate gland. "Knocking out CDC42EP5 in prostate cancer increased the invasive and metastatic abilities of the cells." (PMID 40777026, 2025).
cancer (5 papers, 2018 to 2025). A tumor composed of atypical neoplastic, often pleomorphic cells that invade other tissues. "Research suggested that CDC42EP5 was involved in multiple types of cancer." (PMID 40777026, 2025).
tumor (4 papers, 2020 to 2025). "In conclusion, knockdown of CDC42EP5 inhibited tumor cell activity, migration, invasion, and proliferation, resulting in suppressed tumor growth." (PMID 40777026, 2025). "Interestingly, both solute carrier family 9 isoform A3 regulator factor 1 (SLC9A3R1) and CDC42 effector protein 5 (CDC42EP5) genes were methylated more frequently in the stromal fibroblasts compared withbreast tumour epithelial cells." (PMID 33066013, 2020).